S100A8 (S100 calcium binding protein A8)
Diseases named in the same sentence as S100A8 in open-access papers (continued):
Sharing a sentence is not in itself a finding about the gene and the disease.
pulmonary fibrosis (15 papers, 2015 to 2025). Chronic progressive interstitial lung disorder characterized by the replacement of the lung tissue by connective tissue, leading to progressive dyspnea, respiratory failure, or right heart failure. "S100A8 is thought to be an important target gene that is closely associated with COVID‐19 and pulmonary fibrosis." (PMID 37814484, 2023). "We show that EREG expression is induced by type I interferon and co-expressed with alarmins S100A8 AND S100A9, which aligns our findings to previous clinical studies that associated circulating levels of type I interferon and S100A8/A9 with severity of SSc skin and lung fibrosis." (PMID 36490328, 2022). "At the 24 h time‐point, terms associated with plasmin signaling, blood coagulation, NF‐kB, PDGF, TGF‐β, the Fra‐pathway implicated in pulmonary fibrosis as well as chemokine/inflammatory signaling, that is, S100A8‐complex or regulation of IL1β‐expression targets were identified." (PMID 34713625, 2021). "Pulmonary fibrosis in the lung tissue of PQ-treated rat was associated with interstitial inflammation and accumulated collagen synthesis, as well as a significant increase in the expression of S100A8 and S100A9." (PMID 35540476, 2018). "Thus, S100A8 and S100A9 are associated with lung damage and pulmonary fibrosis by PQ poisoning, and then the mechanism and the potential roles of S100A8 and S100A9 in PQ poisoning require urgent clarification." (PMID 35540476, 2018). "Serum S100A8/S100A9 levels were increased in patients with idiopathic pulmonary fibrosis and acute exacerbation of COPD compared with normal subjects, and negatively associated with pulmonary function." (PMID 39516272, 2025). "In the peripheral blood of SSc‐ILD patients, upregulated genes including S100A8, S100A12, ADAMTS2, IFNG, and SERPINB2 were identified, which have been linked to the progression of lung fibrosis." (PMID 40165483, 2025). "This scheme allowed us to determine the effect of blocking S100A8/A9 in a model of persistent lung fibrosis." (PMID 39012710, 2024). "For example, when combined with RAGE, HMGB1 and S100A8/A9 are suggested to play a role in pulmonary fibrosis." (PMID 36110858, 2022). "A recent proteomic analysis of serum samples from SSc patients also showed S100A8/9 to be increased particularly in lcSSc having lung fibrosis and ATA-positive patients." (PMID 26168983, 2015). "In vivo treatment with an S100A8/A9 inhibitor alleviated experimental lung fibrosis." (PMID 39012710, 2024). "Meanwhile, to evaluate the relationship of S100A8 and S100A9 with PQ-induced pulmonary fibrosis, immunohistochemical (IHC) analysis confirmed the increased expression of these proteins in lung tissue from a rat model of PQ poisoning." (PMID 35540476, 2018). "Furthermore, we have shown that the S100A8/A9 inhibitor paquinimod effectively alleviated fibrotic response and restored AT2 cell populations in a bleomycin-induced lung fibrosis aged mice model." (PMID 39012710, 2024). "High level of S100A8/9 in the BAL fluid and serum in patients has been associated with an extensive lung fibrosis and ATA positivity, although no direct correlation to PFT was found." (PMID 26168983, 2015).
ulcerative colitis (15 papers, 2012 to 2025). An inflammatory bowel disease involving the mucosal surface of the large intestine and rectum. "Cell biology; Proteins; Biochemistry; Molecular biology; Gastrointestinal system; Physiology; Immunology; Biological sciences; S100A8/A9, Ulcerative colitis, Biomarker, C-reactive protein, Inflammatory cytokines." (PMID 32140589, 2020). "The clinical significance of circulating S100A8/A9 (calprotectin) in patients with ulcerative colitis (UC) is poorly understood." (PMID 32140589, 2020). "Previous studies have reported that S100A8-neutralizing antibodies or delivery of S100A8 inhibitors via nanomaterials could attenuate the inflammatory response and enhance the therapeutic efficacy of ulcerative colitis treatment." (PMID 39809743, 2025). "On the other hand, S100A8, S100A9, S100A10, and S100A4 displayed heterogeneous expression patterns in ulcerative colitis patients showing neoplasia." (PMID 23166536, 2012).
acute myeloid leukemia (14 papers, 2018 to 2026). Acute myeloid leukemia (AML) is a group of neoplasms arising from precursor cells committed to the myeloid cell-line differentiation. "S100A8 is also upregulated (using proteomic profiling) in the BM mononuclear cells (MNCs) of acute myeloid leukemia (AML) patients at diagnosis, which is correlated with the worst prognosis." (PMID 37686186, 2023). "Modifying the S100A8/S100A9 ratio by blocking S100A8 with antibodies or adding S100A9 induces the differentiation of acute myeloid leukemia cells and their growth arrest in mouse and human models." (PMID 31437241, 2019). "S100A8 expression in leukemic cells could predict survival in acute myeloid leukemia patients, and the patient with high S100A8 level had the low overall survival." (PMID 36180909, 2022). "However, S100A8 inhibits the differentiation of acute myeloid leukemia cells into mature neutrophils and monocytes." (PMID 31437241, 2019). "Interestingly, elevated S100A8/A9 levels predict Venetoclax resistance in acute myeloid leukemia, suggesting that modulation of calcium-binding proteins could influence both efficacy and toxicity profiles of BCL2 inhibitors." (PMID 40715042, 2025). "In acute myeloid leukemia, S100A8 not only inhibits S100A9-induced terminal differentiation of acute myeloid leukemia (AML) cells, but also favors AML growth." (PMID 36906583, 2023). "S100A4 has been shown to promote acute myeloid leukemia (AML) survival and S100A8 is considered as a prognostic marker for AML." (PMID 34485305, 2021). "Studies on hematological malignancies have found that the expression levels of S100A8 and S100A9 were markedly increased in acute myeloid leukemia (AML), and high expression of S100A8 was a poor prognostic factor for AML patients." (PMID 35371990, 2022). "Deregulations of the expression of the S100A8 and S100A9 genes and/or proteins, as well as changes in their plasma levels or their levels of secretion in the bone marrow microenvironment, are frequently observed in acute myeloblastic leukemias (AML) and acute lymphoblastic leukemias (ALL)." (PMID 33801279, 2021). "Numerous data from the literature suggest that there is a deregulation of the expression of coding genes for S100A8 and/or S100A9 in acute myeloid leukemia (AML)." (PMID 33801279, 2021). "S100A9 induces acute myeloid leukemia (AML) cell differentiation through TLR4–MAPK/ERK–JNK signaling, whereas S100A8 prevents differentiation induced by S100A9 activity and maintains the AML immature phenotype." (PMID 29942307, 2018). "In mice models of acute myeloid leukemia (AML), S100A8 antibodies, but not S100A9 antibodies, induce AML cell differentiation, decrease leukemic burden and increase survival." (PMID 33801279, 2021).
dysplasia (14 papers, 2008 to 2025). A usually neoplastic transformation of the cell, associated with altered architectural tissue patterns. "In this study, we demonstrate that HPV8-positive skin lesions of EV patients are characterized by a dramatic increase of suprabasal alarmin S100A8/A9 expression and stromal inflammation starting in productive lesions and still observed in mild and severe dysplasia." (PMID 29563902, 2018).
Hypertension (14 papers, 2009 to 2025). The presence of chronic increased pressure in the systemic arterial system. "To explore whether there is a potential association between plasma S100A8/A9 levels and HF overload, we first obtained plasma samples from healthy subjects (n = 119) and patients with hypertension-induced HF (n = 143)." (PMID 40860162, 2025). "In summary, our findings revealed that increased miR-21 in aged hearts with hypertension stimuli exacerbated cardiac hypertrophy by suppressing S100a8 expression." (PMID 35907209, 2022). "Neutrophil-derived S100A8/A9 activates cardiac fibroblasts in angiotensin II infusion induced hypertension, implying that S100A8/A9 may mediate neutrophil-induced TGF-β1 upregulation by fibroblasts." (PMID 34359844, 2021). "Based on accumulating experimental evidence, S100A8/A9 also functions as an important regulator of other cardiovascular disorders, such as hypertension, viral myocarditis, autoimmune myocarditis, doxorubicin-induced cardiotoxicity, cardiac hypertrophy, and sepsis-associated cardiomyopathy." (PMID 33282877, 2020). "Thus, novel miR-21/S100a8/NF-κB/NFAT pathway regulatory dysfunction might contribute to the progression of cardiac hypertrophy in aged subjects under hypertension pathophysiology." (PMID 35907209, 2022). "Distributions of RAGE ligands were not different between subjects affected and not affected by hypertension, therefore, hypertensive individuals were not removed from the studied population (log_HMGB1 P=0.786; log_S100A8/9 P=0.927; log_AGEs P= 0.993)." (PMID 30903794, 2019).
Insulin resistance (14 papers, 2013 to 2026). Increased resistance towards insulin, that is, diminished effectiveness of insulin in reducing blood glucose levels. "Importantly, we also detected that circulating levels of endotoxin, LBP, zonulin and S100A8 were associated with insulin resistance, due to the positive correlation with insulin levels and HOMA index and the negative association with QUICKI index." (PMID 38315242, 2024). "Similarly to Gipr-/- BM, LysMΔGipr mice exhibit an aggravated metabolic phenotype in response to prolonged HFD, associated with increased weight gain, steatohepatitis, insulin resistance, myelopoiesis and S100A8/A9 production, as well as impaired ingWAT beiging." (PMID 33717200, 2021). "C3, Saa1 and Saa3, which is regulated by S100a8, encode secretory proteins that can excrete from adipocytes into the local environment, leading to the enhanced inflammation in WAT and insulin resistance." (PMID 31614949, 2019). "Additionally, serum levels of S100A4, S100A8/S100A9, S100A12, and S100B correlate with insulin resistance/T2D, metabolic risk score, and fat cell size." (PMID 35328627, 2022). "Additionally, plasma S100A8/A9 was found to positively correlate with measures of impaired glucose metabolism such as insulin resistance, fasting blood glucose, and glycosylated hemoglobin A1c (HbA1c)." (PMID 24453429, 2013). "Weight loss in obese nondiabetic subjects leads to significantly decreased S100A8/A9 alongside insulin resistance and plasma lipids." (PMID 24453429, 2013). "In addition, we show higher expression of the S100A8 gene in insulin resistance independent of the WBC profile." (PMID 34886800, 2021). "In this sense, we have found an upregulation of different genes related to hypoxia regardless of the degree of insulin resistance, such as ANGPTL4, LPL, S100A8, SLC11A2, HBB, HBA2, and HBD." (PMID 35625760, 2022).
osteoarthritis (14 papers, 2006 to 2025). A noninflammatory degenerative joint disease occurring chiefly in older persons, characterized by degeneration of the articular cartilage, hypertrophy of bone at the margins and changes in the synovial membrane. "Intra-articular injection of S100A8 increased canonical Wnt signaling, whereas canonical Wnt signaling was decreased after the induction of experimental osteoarthritis in S100A9-deficient mice." (PMID 28630526, 2017). "In RA and osteoarthritis patients, three S100 proteins, including S100A8, S100A9, and S100A12 are the most up-regulated biomarkers." (PMID 35796625, 2022). "Another study also showed that serum S100A8/A9 levels were positively correlated with cartilage defects, knee symptoms and increased serum cartilage degrading enzymes in the knee of OA patients, indicating a possible role for S100A8 in osteoarthritis of the knee." (PMID 37497233, 2023). "S100A8 and S100A9 are well-known inflammatory plasma proteins involved in the inflammatory disorders, including osteoarthritis." (PMID 38248784, 2024). "However, both S100-A8 and S100-A9 were decreased in the serum of LCPD patients, showing that LCPD has a different pathogenesis to osteoarthritis." (PMID 26438379, 2015).
viral infection (14 papers, 2012 to 2025). "The analysis of this signature underlined that immune response to viral infection, IL-1, and S100A8/A9 related signaling pathways probably play vital roles in the development of these two clinically correlated diseases." (PMID 36768371, 2023). "On the sixth day, the amounts of galectin-3-binding protein (Lgals3bp), Hpx and S100a8 in the infected mouse blood consistently increased during viral infection, whereas their expression levels in blood were all decreased by HYQ administration (p < 0.05)." (PMID 34867309, 2021). "Our data clearly demonstrate that S100A8/A9 expression is accompanied by strong immune cell infiltration starting during the productive phase of viral infection in EV-lesions." (PMID 29563902, 2018). "Consequently, the hub genes (IL1R1, ICAM1, IRAK1, S100A9, and S100A8), and immune response to viral infection, IL-1 and S100A8/A9 related signaling pathways were selected." (PMID 36768371, 2023). "4-OH-TAM also down-regulated a number of genes, including PGR, S100A8, S100A9, CCND1 and ANEXA1, which are involved in IFN α/β signaling pathway and immune/inflammatory response to viral infection." (PMID 29416786, 2018).
Alzheimer disease (13 papers, 2019 to 2025). A progressive, neurodegenerative disease characterized by loss of function and death of nerve cells in several areas of the brain leading to loss of cognitive function such as memory and language. "Of note, increased expression of S100B, S100A4, S100A6, S100A8, and S100A9 has also been linked with Alzheimer's disease." (PMID 38737767, 2024). "The neurodegenerative diseases for the hub genes and S100a8 included dementia, Parkinson’s disease, neurobehavioral abnormalities, memory disorders, learning disabilities, and Alzheimer’s disease." (PMID 37033380, 2023). "S100A8/A9 concentrations are higher in the serum in multiple sclerosis (MS) patients and in the cerebrospinal fluid (CSF) of Alzheimer’s disease (AD) patients compared with healthy controls." (PMID 35804434, 2022). "Importantly, the immune-response genes of Lcn2, S100a8, and S100a9 have been found that markedly increased in the patients’ hippocampus with Alzheimer's disease." (PMID 34565419, 2021). "Our results highlight a shared neuroinflammatory signature across Alzheimer’s disease (AD), Parkinson’s disease (PD), and Huntington’s disease (HD), characterized by the dysregulation of hub genes such as MMP9, S100A8, S100A9, CCL2, and LCN2." (PMID 41614741, 2025). "Analysis of previously published GE data in Late Onset Alzheimer’s Disease (LOAD) (NCBI GEO: GSE44770,), show that S100A8 and S100A9 are among the highest up-regulated genes in LOAD." (PMID 32469975, 2020). "In contrast, in the brain of APP23 mice, a mouse model for Alzheimer’s disease, S100B, S100A6, and S100A8 show co-localization with Aβ plaques, compatible with astrocyte activation, and the expression level of S100A8 is increased in neural cells." (PMID 31281238, 2019). "Moreover, in mice models of Alzheimer’s disease and traumatic brain injury, we also detected depositions of S100A9, but not S100A8." (PMID 34445262, 2021).
bladder cancer (13 papers, 2010 to 2025). "By contrast, expression of S100A8/S100A9 in sera has been reported to be associated with recurrence-free survival with bladder cancer." (PMID 34650982, 2021). "Overexpression of S100A8 is associated with stage progression, invasion, metastasis and poor survival in human bladder cancer." (PMID 20059769, 2010). "S100A8 is reportedly up-regulated in many cancers, including bladder cancer, and has been implicated in the regulation of tumor cell proliferation and metastasis." (PMID 20096140, 2010). "The results showed that the high expression of S100A8 and CDCA5 in bladder cancer was associated with DSS Significantly correlated with poor prognosis of OS (HR >1, P <0." (PMID 39895787, 2025). "Strikingly, expression of both S100A8 and its correlated genes were strong predictors of the progression of bladder cancer." (PMID 20096140, 2010). "Previous observations that S100A8 expression is enhanced in bladder cancer suggest a role for this protein in the progression of bladder cancer." (PMID 20096140, 2010). "Based on an analysis of the S100A8-correlated genes in the context of gene networks, we identified a putative role for S100A8 in disease progression of bladder cancer." (PMID 20096140, 2010). "The data presented in this study demonstrates that the expression signature of S100A8-correlated genes is able to predict the likelihood of bladder cancer progression." (PMID 20096140, 2010). "This analysis revealed that the molecular signature of S100A8-correlated genes (hazard ratio 15.225, 95% confidence interval = 1.746 to 133.52, P = 0.014) was the only strong predicator of bladder cancer progression." (PMID 20096140, 2010). "Therefore, the present study explored the proliferation, invasion and migration of S100A8 in bladder cancer cells." (PMID 39895787, 2025). "In order to screen better BC cell lines for subsequent studies, we analyzed the gene expression level of S100A8 in BC cell lines through Cancer Cell Line Encyclopedia (CCLE) database, and the results showed that the S100A8 expression of bladder cancer cell line HT-1376 was high." (PMID 39895787, 2025). "Overall, C1 S100A8+ TCs had complex relationships with further development of bladder cancer." (PMID 39691708, 2024). "Nevertheless, the expression of S100A8 in bladder cancer was associated with disease progression in non-muscle-invasive bladder cancer (NMIBC) in more recent studies." (PMID 32722137, 2020). "The serological level of S100A8 and 9 proteins were decreased post-operatively in bladder cancer." (PMID 31528166, 2019). "Alternatively, S100A8 plays a promoting role in the metastasis of CCA and is also a prognostic biomarker for breast and bladder cancer." (PMID 36010914, 2022). "However, whether S100A8 promotes the proliferation, invasion and migration of bladder cancer (BC) is still not completely clear." (PMID 39895787, 2025).
juvenile idiopathic arthritis (13 papers, 2016 to 2025). Juvenile idiopathic arthritis (JIA) is the term used to describe a group of inflammatory articular disorders of unknown cause that begin before the age of 16 and last over 6 weeks. "Prior studies suggested that S100A8/9 levels are associated with disease activity in patients with rheumatoid arthritis and juvenile idiopathic arthritis (JIA)." (PMID 31948488, 2020). "Higher expression of S100A8, but lower expression of S100A9 were found in tears from children with juvenile idiopathic arthritis associated uveitis (JIA-U) compared to those from idiopathic chronic anterior uveitis (I-CAU)." (PMID 38982370, 2024). "This study aimed to investigate the propensity of S100A8/9 and S100A12 as predictive biomarkers of abatacept response in polyarticular-course juvenile idiopathic arthritis (pJIA)." (PMID 38918871, 2024). "A recent study analyzed the relationship between serum S100A8/S100A9 and S100A12 and the maintenance of clinical inactive disease (CID) in patients with polyarticular forms of juvenile idiopathic arthritis (PF-JIA) while on anti-TNF- therapy and disease flare following withdrawal of treatment." (PMID 30828327, 2019).